FTO (FTO alpha-ketoglutarate dependent dioxygenase)
Diseases named in the same sentence as FTO in open-access papers (continued):
Sharing a sentence is not in itself a finding about the gene and the disease.
Insulin resistance (continued). "A potential mechanism related to the interaction of these four particular FTO SNPs with SSBs may be explained by their association to sugar metabolism and insulin resistance, although reports on the role of rs1421085 in glucose metabolism were inconclusive." (PMID 36235854, 2022). "Insulin resistance was associated with the expression level of the FTO gene (padj = 0.037)." (PMID 34063412, 2021). "Furthermore, we demonstrated that increased FTO expression is independently associated with the presence of insulin resistance." (PMID 34063412, 2021). "Besides, single nucleotide polymorphisms (SNPs) in FTO are also strongly associated with T2D, such as variant rs9939609 and rs17817449 of FTO gene, which are important for the development of insulin resistance and occurrence of T2D." (PMID 32110378, 2020). "The association between insulin resistance (IR) and FTO rs9939609 polymorphism is well established." (PMID 32050935, 2020). "Additionally, previous studies showed that rs9939609 variants increased the FTO mRNA transcript important for gene expression involved in glucose homeostasis and insulin resistance." (PMID 29764479, 2018). "Additionally, FTO SNP rs9939609 has been related to systemic inflammation, which is implicated in insulin resistance and diabetogenesis." (PMID 28507607, 2017). "We did not replicate associations with several well-known T2DM genes, including TCF7L2, FTO, IRS1, and KCNQ1, in our Han Chinese population (In our data set, the FTO gene SNPs yielded some associations with insulin resistance related phenotypes in quantitative analyses." (PMID 26139146, 2015). "In regards to indirect mechanism, insulin resistance and hyperinsulinaemia may increase in subjects with FTO risk allele, then resulting in hyperandrogenaemia throuh ovarian co-gonadotrophic effects." (PMID 24466303, 2014). "The discrepancy in findings concerning the association between FTO rs9939609 variants and insulin resistance among other studies including our results indicates that the effect of FTO rs9939609 variants on insulin resistance may be influenced by other variables including: gender, age and ethnic." (PMID 29764479, 2018). "Moreover, FTO variant rs9939609 was associated with variables of insulin resistance." (PMID 20092643, 2010). "TCF7L2 has been strongly linked to elevated HbA1c levels and an increased risk of T2D, FTO rs9939609 variant has been linked to high HbA1c levels and insulin resistance, and CAPN10 has been associated with insulin resistance and T2D." (PMID 39275336, 2024). "A recent study has confirmed that individuals with extra mass and FTO rs9939609 risk genotype had higher levels of BMI, total cholesterol, insulin, high-density lipoprotein (HDL) and homeostatic model assessment for insulin resistance (HOMA-IR)." (PMID 37200795, 2023). "The FTO gene was considerably more expressed in obese children and patients with established insulin resistance (p = 0.008)." (PMID 34912641, 2021). "In T2D, miR-495 inhibited FTO expression, thus promoting the transformation of macrophages into M1-type pro-inflammatory macrophages, and aggravated insulin resistance and adipose tissue inflammation." (PMID 34150765, 2021). "We showed significantly increased expression of the FTO gene in obese children and in patients with documented insulin resistance." (PMID 34063412, 2021). "Previous studies suggested that FTO gene polymorphisms were commonly correlated with metabolic disorders, especially central obesity, low-density lipoprotein (LDL), insulin resistance, and hypertriglyceridemia, which are tightly related to NAFLD." (PMID 33817272, 2020). "In the majority of the examined porcine tissues, changes in FTO expression in response to either HE diet (leading to insulin resistance) or LE diet (leading to significant growth retardation) were uniform." (PMID 32747736, 2020).
Insulin resistance (continued). "There is compelling evidence that omental adipose tissue (OAT) FTO expression is associated with adiposity, whereas SAT FTO expression is associated with insulin resistance." (PMID 26691922, 2015). "Participants with high BMI and insulin resistance have an even larger response, as have non-risk allele carriers for the FTO gene." (PMID 37884680, 2023). "Candidate gene studies have suggested that FTO variation is associated with insulin resistance or hyperinsulinaemia in women with PCOS, independent of BMI." (PMID 35771237, 2022). "FTO expression was also significantly higher in patients with documented insulin resistance." (PMID 34063412, 2021). "Furthermore, a higher FTO expression is independently related to the incidence of insulin resistance." (PMID 34912641, 2021). "Furthermore, while FTO variants are linked to insulin resistance and glucose intolerance in PCOS, there is paucity of literature on the relationship between FTO variants and hyperandrogenaemia." (PMID 32050935, 2020). "Omentin V109D and FTO rs9939609 genetic variations may change insulin metabolism and have key roles in developing T2D through insulin resistance." (PMID 31200723, 2019). "Risk alleles like FTO, ADIPOQ, INSR, IRS1, IRS2, PPARG, CAPN10 may leave individuals more vulnerable to insulin resistance and/or adiposity (which can result in peripheral insulin resistance), leading to high circulating insulin." (PMID 31367382, 2019). "Thus, Indonesian obese female adolescents can shed additional light on the FTO rs9939609 effect on insulin resistance by providing data from a genetically distinct group within Asia." (PMID 29764479, 2018). "FTO rs9939609 common variant has been significantly related with increased insulin resistance in obese female adolescents (p < 0.001), but not in male adolescents in Chile after adjustment for body mass index (BMI)." (PMID 29764479, 2018). "Our results of a negative association between insulin sensitivity and the FTO risk allele in males only, are not in accordance with studies in children and adolescents that find a positive association between insulin resistance and the FTO risk allele mainly in females." (PMID 33684170, 2021). "FTO rs9939609 variant may not be associated with insulin resistance in Indonesian obese female adolescents." (PMID 29764479, 2018). "In conclusion, FTO rs9939609 variant may not be associated with insulin resistance in Indonesian obese female adolescents." (PMID 29764479, 2018). "In insulin-resistant (IR) children, MEG3, ATF4, FTO, ACACA, and SREBP1 were reduced, while FASN was increased." (PMID 40806129, 2025). "FTO and ATF4 were negatively correlated with adiposity and insulin resistance indices." (PMID 40806129, 2025). "FTO is BCAA sensor and brings essential amino acids to mechanistic target of rapamycin complex 1 (mTORC1), leading to hiperactivated mTORC1 signalling and insulin resistance." (PMID 37200795, 2023). "The abundance of FTO and TMEM18 in the spermatozoa of rats under CR were positively correlated with sperm concentration, while the testes’ TMEM18 expression was also positively correlated with sperm vitality and negatively correlated with insulin resistance." (PMID 36289871, 2022).
glioma (65 papers, 2019 to 2026). A benign or malignant brain and spinal cord tumor that arises from glial cells (astrocytes, oligodendrocytes, ependymal cells). "The loss of FTO in aggressive glioma would therefore lead to the stabilization and accumulation of EREG mRNA, fueling a proliferative signaling cascade." (PMID 40970086, 2025). "The N6-methyladenosine (m6A) demethylase, Fat mass and obesity-associated protein (FTO), is a critical regulator of gene expression, but its precise role in glioma remains controversial." (PMID 40970086, 2025). "We then employed in vitro gain- and loss-of-function studies in U251 and U87MG glioma cell lines, coupled with an in vivo xenograft model, to systematically investigate the biological role of FTO." (PMID 40970086, 2025). "Our analysis revealed that lower FTO expression is significantly associated with higher tumor grade and poorer overall survival in glioma patients." (PMID 40970086, 2025). "This study aimed to elucidate the function and underlying molecular mechanisms of FTO in glioma progression." (PMID 40970086, 2025). "Gliomas have been linked to the FTO gene, which is responsible for demethylating m6A in single-stranded RNA through alpha-ketoglutarate-dependent dioxygenase." (PMID 38173044, 2024). "FTO expression is also linked to the decreased apoptosis and increased proliferation of glioma cells, and its inhibition suppresses GSC growth and self-renewal." (PMID 38474421, 2024). "A possible mechanism for this effect is the role FTO has in the context of the frequent IDH1/2 mutations in gliomas." (PMID 37444417, 2023). "Noticeably, they found that 11 of 13 m6A-related regulators were strongly linked to overall survival (OS), among which FTO was consistently a protective gene among all types of gliomas." (PMID 34381710, 2021). "The low expression of FTO were associated with poor prognosis in gliomas, although there have been a contentious and divisive." (PMID 33240891, 2020). "However, R-2HG inhibits FTO in glioma, causing MYC/CEBPA mRNA methylation, disrupting the stability of these oncogene transcripts and inhibiting the activation of downstream oncogene pathways." (PMID 40469294, 2025). "Our initial analysis of over 1,000 glioma patients from the TCGA and CGGA databases, corroborated by our own clinical samples, consistently showed that FTO expression is significantly downregulated in high-grade gliomas and is strongly associated with poor overall survival." (PMID 40970086, 2025). "This subset of progressed gliomas exhibiting a loss of IDH1 heterozygosity (resulting in reduced D-2-HG generation like that seen in BT142 cells) are thus likely to show sensitivity to FTO inhibitors, similarly to IDH1wt gliomas." (PMID 38445960, 2024). "Similarly, blocking the FTO/m6A/MYC/CEBPA-associated signaling pathway using R-2HG has shown promise in inhibiting the rapid development of glioma." (PMID 38649363, 2024). "The exact mechanisms underlying the dominant influence of FTO in regulating glioma m6A dynamics and cell proliferation remains unclear, but might be explained by differences in catalytic activity, RNA substrate preferences, and cellular localization." (PMID 38445960, 2024). "IDH1/2 mutations are predominantly associated with lower-grade glioma, and it may be the case that endogenous R-2HG production in GSCs suppresses FTO levels, thus reducing oncogene expression and limiting progression by maintaining m6a levels." (PMID 37444417, 2023). "Interestingly, we observed that the upregulation of ALKBH5 acts as a risk factor, while the downregulated of FTO acts as a risk factor in gliomas." (PMID 33264518, 2021). "Furthermore, the expression trend of WTAP and FTO that same as our result was positively associated with the malignant progression in gliomas." (PMID 32500031, 2020). "These rescue experiments confirm that FTO suppresses glioma cell proliferation and cell cycle progression by inhibiting the PI3K/Akt signaling axis." (PMID 40970086, 2025).
glioma (continued). "Overall, these findings indicate that the fusion of GA-MSCs with glioma cells promotes macrophage recruitment and M2-like polarization through FTO-mediated CSF1 secretion within the TME." (PMID 40287444, 2025). "Although reports suggest that FTO can promote the onset of gliomas, notably, in most cases, the expression of FTO in gliomas is significantly negatively correlated with tumour malignancy." (PMID 40469294, 2025). "These in vivo data provide compelling evidence that FTO acts as a potent suppressor of glioma tumor growth." (PMID 40970086, 2025). "These proteins, such as FTO, are demethylases that reverse the high methylation levels typically found in gliomas." (PMID 40469294, 2025). "Our investigation into the underlying mechanism led us to identify EREG as a novel and critical downstream target of FTO in glioma." (PMID 40970086, 2025). "The downregulation of FTO in high-grade glioma disrupts this regulatory brake, leading to uncontrolled tumor growth." (PMID 40970086, 2025). "In summary, our study delineates a clear tumor-suppressive pathway in glioma: FTO demethylates and destabilizes EREG mRNA, which limits EREG-mediated activation of the PI3K/Akt pathway." (PMID 40970086, 2025). "Quantitative analysis confirmed that FTO expression was significantly lower in high-grade gliomas (WHO grades III-IV) compared to low-grade gliomas (WHO grades I-II)." (PMID 40970086, 2025). "IHC and qRT-PCR analyses showed a progressive decrease in FTO protein and mRNA levels with increasing glioma grade, consistent with the database results." (PMID 40970086, 2025). "These conflicting reports underscore the need for a comprehensive investigation into FTO’s precise function and mechanism in glioma." (PMID 40970086, 2025). "Through a comprehensive approach combining large-scale clinical data analysis, in vitro functional assays, and an in vivo xenograft model, we demonstrate that a FTO-EREG-PI3K/Akt signaling axis plays a pivotal role in controlling glioma proliferation." (PMID 40970086, 2025). "Although FTO has broad prospects as a therapeutic target for glioma, its specific efficacy still needs to be validated in further clinical trials." (PMID 40469294, 2025). "To investigate the clinical relevance of FTO in glioma, we analyzed transcriptomic and clinical data from the CGGA and TCGA cohorts." (PMID 40970086, 2025). "Conversely, to mimic the low FTO expression observed in high-grade glioma, we knocked down FTO using two independent shRNAs (shFTO-1, shFTO-2)." (PMID 40970086, 2025). "Associations between glioma malignancy grade and the expression of m6 A writers (METTL3, METTL14, WTAP, and RBM15), the reader YTHDF, and erasers (ALKBH5 and FTO) are shown." (PMID 40382536, 2025). "Decreased FTO expression in clinical samples is correlated with higher glioma grades and poorer clinical outcomes." (PMID 40469294, 2025). "In this study, we definitively establish the m6A demethylase FTO as a critical tumor suppressor in glioma." (PMID 40970086, 2025). "In this study, we first leveraged large-scale public datasets (TCGA and CGGA) to confirm the correlation between low FTO expression and adverse clinical features in a cohort of 1,027 glioma patients." (PMID 40970086, 2025). "Some studies have shown that FTO expression is negatively correlated with glioma malignancy and that patients with lower FTO levels have a poorer prognosis." (PMID 40970086, 2025). "Prognostic studies suggest that FTO can predict poor outcomes in glioma patients, and inhibitors targeting FTO have shown promise in reducing tumorigenicity and aggressiveness in glioma models." (PMID 38474421, 2024). "IGF2BP3 downregulated the expression of both m6A-associated writers (METTL3, METTL14) and erasers (FTO, ALKBH5), with a specific focus on FTO due to its more pronounced effect in both U87MG and GL261 glioma cell lines." (PMID 38167409, 2024).
glioma (continued). "On one hand, IDH1mut generation of D-2-HG can trigger gliomagenesis by interfering with DNA/histone methylation, HIF1α, and DNA damage repair, while on the other acting as a growth suppressor of established gliomas, via mechanisms such as FTO inhibition." (PMID 38445960, 2024). "Pursuant to this point, a recent publication identified that D-2-HG reduces glioma cell growth by inhibiting the m6A epi transcriptome regulator, FTO." (PMID 39596840, 2024). "Taken together, these experiments show that pharmacologic inhibition of FTO reliably reduces IDH1wt glioma cell growth rates both in vitro and in vivo." (PMID 38445960, 2024). "We show that IDH1mut production of D-2-HG is capable of reducing glioma cell growth via inhibition of the m6A epitranscriptomic regulator, FTO, with resultant m6A hypermethylation of a set of mRNA transcripts." (PMID 38445960, 2024). "This study confirms that D-2-HG suppresses glioma growth in a variety of model systems and demonstrates that a contributing mechanism involves D-2-HG–mediated inhibition of the RNA m6A demethylase FTO." (PMID 38445960, 2024). "Our work provides evidence that selective inhibition of the m6A epitranscriptomic regulator FTO attenuates growth in IDH1wt glioma, recapitulating the clinically favorable growth phenotype seen in the IDH1mut subtype." (PMID 38445960, 2024). "To exploit the growth-attenuating effects of FTO inhibition, we tested the possibility of targeting FTO and m6A regulation as a novel treatment strategy for IDH1wt gliomas." (PMID 38445960, 2024). "To elucidate the role of m6A modifiers in regulating AS of LINC00475, we initially assessed the expression levels of METTL3, ALKBH5, and FTO in glioma cells." (PMID 38405130, 2024). "We show that IDH1mut-generated D-2-HG can reduce glioma growth via inhibition of the m6A demethylase, FTO." (PMID 38445960, 2024). "R-2-hydroxyglutarate (R-2HG) has similar effects, which reduces MYC/CEBPA transcript stability and suppresses relevant pathways, with similar effects seen in glioma, suggesting R-2HG’s potential for targeting FTO/m6A/MYC/CEBPA signaling in FTO-high cancers." (PMID 39459530, 2024). "We further revealed that the IGF2BP3/MIB1/FTO pathway forms a positive feedback loop in both T98G cells and primary cultured human glioma cells." (PMID 38167409, 2024). "This conversion is generally pro-tumorigenic, except that in AML and glioma cells this oncometabolite inhibits FTO enzymatic activity and m6A accumulation on FTO targets, thus eliciting tumor suppressing effects in vitro and in vivo." (PMID 37612540, 2023). "In contrast, various pieces of evidence challenge the notion of cancer-promoting effects of FTO in gliomas." (PMID 37964279, 2023). "Consistently, FTO protein level was lower in the core and intermediate regions, particularly within the core region, than in the peripheral region of glioma." (PMID 36718644, 2023). "Regarding glioma, FTO interacts with FOXO3a to promote its transcriptional activity and suppresses glioma aggressiveness." (PMID 36718644, 2023). "Mechanistically, FTO regulates the maturation of primary miR-10a via the m6A-dependent pathway to modulate glioma progression." (PMID 38072944, 2023). "miR-27a-3p overexpression promoted hypoxia-challenged glioma cell aggressiveness, whereas FTO overexpression partially diminished the oncogenic effects of miR-27a-3p overexpression." (PMID 36718644, 2023). "Under hypoxia, FTO overexpression inhibited glioma cell viability, cell migration, and cell invasion." (PMID 36718644, 2023). "While seemingly a promising novel therapeutic target, there are conflicting reports, including reduced FTO expression levels in more aggressive glioma tumour subtypes, with low FTO expression levels significantly associated with poor survival outcomes." (PMID 36831575, 2023).